NLRP3 (NLR family pyrin domain containing 3)
Diseases named in the same sentence as NLRP3 in open-access papers (continued):
Sharing a sentence is not in itself a finding about the gene and the disease.
melanoma (continued). "Specifically, transcriptomic analysis in M-MDSCs revealed 992 DEGs (|FC| ≥ 1.5, FDR< 0.05) between Nlrp3-/- and WT melanoma-bearing animals with 318 and 674 genes to be up- and downregulated, respectively." (PMID 36032139, 2022). "Recent studies have demonstrated that excessive activation of the NLRP3 inflammasome enhances the invasion and metastasis of multiple tumours, including melanoma, hepatocellular carcinoma and pancreatic cancer." (PMID 35707534, 2022). "The capability of NLRP3 to response to various signals contributed to its biological significance in many diseases, including transplantable tumors, melanoma, and colorectal cancer." (PMID 36276158, 2022). "Our TCGA analysis also revealed a contrasting correlation of NLRP3 expression and survival in patients with melanoma and lung cancer, building upon the proposed dual role of NLRP3 in cancer." (PMID 36032139, 2022). "Our results demonstrate that the NLRP3/IL-1β pathway is activated in MDSCs in melanoma-bearing animals." (PMID 36032139, 2022). "Recently, NLRP3 activity in melanoma was shown to upregulate PD-L1 in both tumor cells and MDSCs through tumor-intrinsic and tumor-host signaling pathways." (PMID 35631400, 2022). "Overall, these data confirm the in vitro observation and suggest the induction of IL‐6/STAT3 following NLRP3 inflammasome activation as an integral driver of melanoma progression." (PMID 34531850, 2021). "The concept of NLRP3 being an intrinsic pathway that participates in melanoma progression has been independently validated by a comprehensive study that relates NLRP3 expression in melanoma cells in response to immunotherapy." (PMID 33649199, 2021). "NLRP3 is particularly relevant to the processing of IL-1β in melanoma because NLRP3 is constitutively expressed in melanoma cell lines and NLRP3 polymorphisms are linked to increased risk to develop melanoma." (PMID 33649199, 2021). "Using cancer databases, we found higher expression of NLRP3 in skin biopsies of melanoma lesions compared to normal skin and with NLRP3 expression positively correlated with expression of IL-1β." (PMID 33649199, 2021). "The reduction in tumor growth in wild-type mice fed OLT1177 was also observed using implanted YUMM melanoma cells; thus, specific targeting of NLRP3 is not limited to B16F10 cells." (PMID 33649199, 2021). "In this study, we elucidated a novel mechanism that demonstrates how NLRP3 activity in melanoma drives inflammation resulting in increased expression of immunosuppressive genes in MDSCs." (PMID 34531850, 2021). "Using a mouse model of melanoma, we report here that NLRP3 activation induces IL‐1β-mediated IL‐6 production resulting in STAT3 activation." (PMID 34531850, 2021). "Recent studies have demonstrated the role of Nod-like receptor protein 3 (NLRP3) inflammasome in promoting melanoma progression." (PMID 34747716, 2021). "It is notable that this data is consistent with a recent study that also recognized a relationship between the tumor-intrinsic NLRP3 inflammasome and the recruitment of MDSCs in the B16/F10 melanoma model." (PMID 34638239, 2021). "We have previously shown that metastatic melanoma cells display constitutively active NLRP3 resulting in spontaneous IL-1β production and release." (PMID 34531850, 2021). "Recently, we have reported constitutive NOD-like receptor protein 3 (NLRP3) activation and NLRP3 inflammasome formation in melanoma." (PMID 34531850, 2021). "In comparison to the levels of IL-1β typically generated via NLRP3 activation in myeloid cell populations, the levels of IL-1β secretion via the tumor-intrinsic NLRP3 pathway in both murine melanoma models and in human melanoma cell lines are minimal." (PMID 34638239, 2021). "Oral administration of a single NLRP3 inhibitor (OLT1177) reduces melanoma growth and melanoma-associated myeloid-derived suppressor cell expansion." (PMID 33649199, 2021).
melanoma (continued). "Rather than a response mechanism to inhibition of checkpoints, the present study revealed that NLRP3 drives melanoma progression independently of checkpoint inhibition." (PMID 33649199, 2021). "In this study, we demonstrate that activation of NLRP3 and the subsequent formation of the NLRP3 inflammasome have clear implications for melanoma progression, mostly by generating a tumor-permissive environment via MDSC expansion." (PMID 33649199, 2021). "These in vitro findings demonstrate constitutive NLRP3 inflammasome activation in human melanoma cells and its role in the processing and secretion of IL-1β." (PMID 33649199, 2021). "Altogether, these findings reveal how metastatic melanoma cells amplify IL-6 signaling through an NLRP3-mediated autoinflammatory loop, which in turn, drives IL-6/STAT3 regulated immunosuppressive gene expression in PMN-MDSCs." (PMID 34531850, 2021). "The mechanisms of the NLRP3 inflammasome in melanoma and other skin cancers are not clearly understood, but several reports have demonstrated the involvement of NLRP3 inflammasome components in tumorigenesis." (PMID 34064909, 2021). "Here, we link NLRP3 activity in melanoma cells to the IL-1β induced-IL‐6/STAT3 axis, thus providing an additional mechanism to target STAT3 signaling in melanoma." (PMID 34531850, 2021). "The disastrous effect of NLRP3 inflammasome in melanoma is owed to its suppression of NK cell activation, necessary for the release of IFN-γ and killing of tumor cells, therefore, ultimately increasing lung metastasis." (PMID 33540625, 2021). "We recently reported that constitutively active NLRP3 in melanoma cells induces IL-1β and IL-6 in the host, resulting in the expansion of MDSCs." (PMID 34531850, 2021). "Overall, we conclude that NLRP3 of melanoma origin functions as an intrinsic signal for tumor progression." (PMID 33649199, 2021). "To determine the role of NLRP3 in IL-1β processing in melanoma, we specifically targeted NLRP3 in human melanoma cell lines." (PMID 33649199, 2021). "Gene amplification in NLRP3 has been identified in select cancer types, including breast cancer, ovarian cancer, and melanoma." (PMID 34638239, 2021). "A constitutive activation of the NLRP3 inflammasome in late-stage human melanoma cells with the autonomous secretion of active IL-1β has been demonstrated." (PMID 32796686, 2020). "The treatment of metastatic human and mouse melanoma cell lines with the anti-inflammatory phytochemical thymoquinone was shown to hamper the metastasis process by inhibition of the NLRP3 inflammasome." (PMID 32796686, 2020). "In particular, NLRP3 inflammasome was shown to be constitutively expressed and activated in human melanoma cells." (PMID 32733479, 2020). "In melanoma, it was shown that NLRP3 in the TME weakens the anti-tumor immune response to a cancer vaccine, by assisting the migration of myeloid-derived suppressor cells (MDSCs), thus suppressing the T cell response." (PMID 32733479, 2020). "Conversely, others reported that NLRP3 inflammasome activation and the consequent release of IL-1β and IL-18 promoted tumor growth, proliferation, invasion, and metastasis in lung cancer, melanoma, breast cancer, and head and neck squamous cell carcinoma." (PMID 31200447, 2019). "Late-stage human melanoma cells constitutively secrete IL-1β through spontaneous activation of the NLRP3 inflammasome, promoting inflammatory environment, macrophage chemotaxis, and angiogenesis." (PMID 31439870, 2019). "Targeting the NLRP3 inflammasome reduces tumor progression in different mouse models, including melanoma, breast and oral squamous cell carcinoma models." (PMID 31552036, 2019). "Another study evaluated the association of the genetic polymorphisms of NLRP3 (Q705K and rs10733113), CARD-8 (rs2043211), and NLRP1 (rs6502867 and rs12150220) in Swedish patients with sporadic malignant melanoma (MM)." (PMID 30447690, 2018).
melanoma (continued). "It is known that the NLRP3 inflammasome is constitutively activated in melanoma cells, and late-stage melanoma cells can autonomously secrete IL-1β." (PMID 27229305, 2016). "In concert with this data, Nlrp3−/− mice challenged intravenously with B16F10 melanoma and RM-1 prostate carcinoma cells had significantly fewer metastasis compared to wild-type mice." (PMID 24273542, 2013). "Constitutively active NLRP3 inflammasome and IL-1β secretion were observed in late stage melanoma cells." (PMID 23065753, 2012). "Additionally, human melanoma cells constitutively express and activate NLRP3, leading to autoinflammation through caspase-1 activity and the production of biologically active IL-1β." (PMID 41017127, 2025). "Additionally, the activation of NLRP3 inflammasome in melanoma cells can promote cell resistance to death by regulating autophagy and mitochondrial energy production." (PMID 41560727, 2025). "Furthermore, the key molecule of pyroptosis NLRP3 is required for the TH2 cell transcriptome program in CD4( +) T cells, and NLRP3 deficiency promotes melanoma growth." (PMID 38229080, 2024). "We searched PubMed and Google Scholar to find articles published in the last 10 years or so, using keywords including NLRP3, inflammasome, immune response, IL-1β, IL-18, pyroptosis, melanoma, leukemia, breast cancer, colon cancer, lung cancer, and other cancer types." (PMID 39769450, 2024). "Recent evidence suggests that upregulation of the NLRP3 inflammasome may aggravate inflammatory responses in melanoma." (PMID 39275245, 2024). "In addition, NLRP3-mediated immune and inflammatory responses also play an important role in the growth and progression of melanoma, as well as its resistance to immunotherapy." (PMID 39769450, 2024). "However, other studies have reported that NLRP3 inflammasome activation and the production of IL-1β and IL-18 can promote melanoma growth." (PMID 39769450, 2024). "Moreover, combining anti-programmed cell death-(PD)-1 therapy with NLRP3 inhibition suppressed primary melanoma progression and distant melanoma metastases more effectively than anti-PD-1 monotherapy." (PMID 39769450, 2024). "The NLRP3 inflammasome has been associated with both positive and negative predictive outcomes in melanoma patients." (PMID 39769450, 2024). "However, additional pre-clinical and clinical studies are required to clearly understand the significant role of NLRP3 in melanoma progression, as well as providing resistance to immunotherapy." (PMID 39769450, 2024). "Thus, current findings suggest a dual role for NLRP3 in melanoma, where its activation can promote or inhibit tumor growth and progression, depending on the context." (PMID 39769450, 2024). "NLRP3 is required for melanoma growth, progression, and immune response." (PMID 37715239, 2023). "In the present study, we combined NLRP3 inhibition and dexamethasone in mice with melanoma." (PMID 36672229, 2023). "In contrast, VEGFA, TGFβ receptor, NLRP3 inflammasome and Oncostatin M signaling were selectively upregulated, while antigen processing and pattern recognition receptor activity genes were downregulated in melanoma mDC." (PMID 37938561, 2023). "Furthermore, numerous studies show that the NLRP3 promotes melanoma cell lung metastasis and supports HCC metastasis in mouse lung metastasis models." (PMID 37715239, 2023). "Studies have shown that NLRP3 deletion could significantly reduce the lung metastasis of melanoma by activating NK cells." (PMID 37950289, 2023). "Further studies have established the association of NLR family pyrin domain containing 3 (NLRP3) and Absent in melanoma-2 (AIM2), both of which are involved in inflammasome activation, with VaD and CCH." (PMID 37309012, 2023). "Additionally, the activation of NLRP3 inflammasome in melanoma cells can promote tumor cell growth and resistance to death by regulating autophagy and mitochondrial energy production." (PMID 37715239, 2023).
melanoma (continued). "Similarly, NLRP3 inflammasomes promote melanoma growth by activating caspase-1 and producing IL-1β, which leads to suppression of anti-tumor immunity generated by NK cells and T cells." (PMID 37020871, 2023). "In the process of the incidence and development of human cutaneous MM, NLRP3 promotes the developmental progress of melanoma by affecting host tumor immunity and promoting the proliferation and differentiation of A375 cells in melanoma as well as regulating its microenvironment." (PMID 35874899, 2022). "SNPs of NLRP3 and particularly of NLRP1 are associated with the development of melanoma." (PMID 36293159, 2022). "However, the role of NLRP3 in melanoma is unclear as another recent report found its activity induces cell death in BRAF inhibitor-resistant melanomas and improves prognosis." (PMID 35515106, 2022). "LPS/ATP triggered the activation of NLRP3 inflammasomes, including caspase-1 activities, which enhanced the secretion of IL-18 and IL-1β, consequently resulting in an enhanced migratory ability of melanoma cells." (PMID 35682990, 2022). "However, as to other cancers, such as fibrosarcoma, melanoma, gastric carcinoma, and lung cancer, NLRP3 functioned as a deleterious protein owing to its ability to suppress activation of NK cells that secrete IFN-γ and kill tumor cells." (PMID 36276078, 2022). "This discrepancy may account for the different strains of Nlrp3-/- mice used and/or the different melanoma cell numbers and method of injections (mixing with Matrigel) used in the two studies." (PMID 36032139, 2022). "Furthermore, it was suggested that expression and activation of the NLRP3 inflammasome in human melanoma cells correlate with malignancy and with spontaneous IL-1β secretion by late-stage melanoma." (PMID 36293159, 2022). "Tumor regression in melanoma-bearing Nlrp3-/- mice was accompanied by significantly increased frequencies of tumor-infiltrating CD45+ leukocytes, CD8+ lymphocytes, which exhibited elevated IFN-γ expression, and NK1.1+ cells, as well as increased frequencies of CD4+ T cells, compared to WT mice." (PMID 36032139, 2022). "Finally, targeting NLRP3 expression in B16.F10 melanoma cells attenuated tumor growth and limited the expansion of MDSCs." (PMID 36032139, 2022). "In this investigation we demonstrate the tumor-promoting role for NLRP3 signaling in melanoma." (PMID 33649199, 2021). "NLRP3 plays vital roles in melanoma tumorigenesis, progression, and immune response, however, its alterations association with ICI efficacy remains unclear." (PMID 34747716, 2021). "However, a recent study reported that anti-PD-1 therapy increased melanoma-NLRP3 activity, resulting in increased PD-L1 expression in the tumor." (PMID 34531850, 2021). "Here, we demonstrate that NLRP3 activation in melanoma cells drives tumor progression in mice." (PMID 33649199, 2021). "Thus, targeting NLRP3 represents an innovative strategy for treating melanoma, especially in the context of immunotherapy resistance tumors." (PMID 33649199, 2021). "Recent studies demonstrated that NLRP3 inflammasome upregulation may inhibit the inflammatory responses in melanoma." (PMID 34747716, 2021). "Before evaluating the association of NLRP3 mutations with ICI efficacy, we explored the influences of common clinical features (i.e., TMB, age, gender, stage, and treatment type) with 336 ICI-treated melanoma patients." (PMID 34747716, 2021). "We demonstrate active NLRP3 inflammasome in malignant melanoma skin biopsies." (PMID 33649199, 2021). "Although the mechanism of influence of NLRP3 on Treg activity was not investigated in this study, these data support the hypothesis of NLRP3 as an intrinsic melanoma mechanism that drives inflammation and immunosuppression." (PMID 33649199, 2021). "Whereas these studies indicate a possible role for NLRP3 in melanoma progression, the biological function for NLRP3 in melanoma remains unclear." (PMID 33649199, 2021).
melanoma (continued). "In this study, we investigate whether NLRP3-dependent IL-1β production observed in melanoma cells drives IL-6/STAT3 signaling and whether this influences MDSC activity." (PMID 34531850, 2021). "In NLRP3- or caspase-1-knockout macrophages, the ability to promote the migration and invasion of melanoma cells was, similarly, greatly diminished and the metastatic potential of melanoma tumor cells was suppressed." (PMID 33613533, 2020). "NLRP1 and NLRP3 are two key NLRP family members for IL-1β secretion in melanoma." (PMID 33396632, 2020). "In addition, inactivation of NLRP3 inflammasome has also been found to reduce IL-1β expression and halt development of melanoma." (PMID 33613533, 2020). "However, NLRP3- or caspase-1-knockout macrophages exhibited greatly diminished ability to promote the migration and invasion of melanoma cells." (PMID 31439870, 2019). "In addition, NLRP3 inflammasome pathway contributed to the development and progression of last stage human melanoma cells, its promoted role in cancer formation was consistent with the present results." (PMID 30696442, 2019). "In addition, treatment with celastrol, an inhibitor of NLRP3 inflammasome, reduced the potency of macrophages to stimulate migration and invasion of melanoma cells." (PMID 31439870, 2019). "Furthermore, inhibition of the NLRP3 inflammasome in myeloid cells by a pharmacological inhibitor such as celastrol resulted in the decreased metastatic potential of melanoma cells." (PMID 31439870, 2019). "However, recent studies have confirmed that NLRP3 inflammasome with excessive activation promotes the metastasis of multiple tumors including melanoma cells and hepatocellular carcinoma cells." (PMID 29386037, 2018). "Interestingly, the presence of NLRP3 led to a decrease in survival during B16F10 melanoma challenge and subsequent vaccination with B16-pulsed dendritic cells." (PMID 24273542, 2013). "Therefore, targeting NLRP3 in tumors to inhibit the immunosuppressive function of MDSCs may constitute an investigational strategy for the treatment of melanoma, especially in the environment of immunotherapy-resistant tumors." (PMID 38609997, 2024). "To conclude, our work shows evidence of very low NLRP3 expression and IL‐1β secretion by melanoma cells and highlights the differences between cutaneous and uveal melanoma, providing data that may contribute to future melanoma translational research." (PMID 36707938, 2023). "Therefore, targeting tumor-derived NLRP3 inflammasome may represent a novel therapeutic strategy to enhance antitumor immunity and improve the efficacy of immunotherapy in melanoma." (PMID 37715239, 2023). "Furthermore, single nucleotide polymorphisms (SNPs) of NLRP3 are associated with Crohn’s disease, a risk factor for CRC, and a gain-of-function mutation results in poorer survival of patients suffering from CRC and increases the risk of developing melanoma." (PMID 36293159, 2022). "The expansion of MDSCs is induced in melanoma through NLRP3/IL-1 signaling, suggesting that NLRP3 inhibitors may restore T cell function through reducing the numbers of tumor MDSCs, and the combined treatment with NLRP3 inhibitor and anti-PD-1 is more effective." (PMID 36131911, 2022). "Moreover, modulation of the tumor microenvironment through the inhibition of the NLRP3 inflammasome could suppress the migration and invasion of melanoma cells." (PMID 34457117, 2021). "Our results demonstrate that IL-1β produced by macrophages stimulates the metastatic potential of melanoma cells, such as migration and invasion properties, showing the essential role of myeloid cells in the production of IL-1β in tumor microenvironment through activation of the NLRP3 inflammasome." (PMID 31439870, 2019). "We profiled three murine cancer cell lines: B16F10 (melanoma), 4T1 (breast cancer) and CT26 (colon cancer) for the expression of cell death effector gasdermin D, and the components of NLRP3 inflammasome." (PMID 39737979, 2024).